GDF15 (growth differentiation factor 15)
Diseases named in the same sentence as GDF15 in open-access papers (continued):
Sharing a sentence is not in itself a finding about the gene and the disease.
fibrosis (20 papers, 2020 to 2026). the formation of excess fibrous connective tissue in an organ or tissue in a reparative or reactive process. "Previous studies have also found that GDF-15 levels increase in various chronic liver diseases and are associated with the severity of fibrosis." (PMID 41157623, 2025). "Two recent studies have shown GDF-15 to be associated with biopsy-proven fibrosis in the kidneys, the first in patients with IgA nephropathy and the other in idiopathic membranous nephropathy." (PMID 32089755, 2020). "Overall, targeting GDF-15 is a very appealing therapeutic field for those pathologies where GDF-15 activity has demonstrated a clear impact, such as fibrosis-associated diseases." (PMID 39000420, 2024). "A GDF15 cut-off value of 415.41 pg/mL predicted advanced fibrosis with 92.9% sensitivity and 85.9% specificity." (PMID 36430499, 2022). "Overall, the subjects with initial advanced fibrosis exhibited considerably higher basal GDF15 serum levels (688 vs. 339 pg/mL; p < 0.001) and also experienced a transient GDF15 increase during the first 3 months of weight loss therapy." (PMID 36430499, 2022). "In univariable analysis, higher serum GDF-15 concentrations were associated with higher liver VCTE-derived kPa measurements, and serum GDF-15 concentrations were higher in patients with ≥F2 fibrosis." (PMID 34663793, 2021). "In future research, it would be beneficial to assess the reliability of GDF15 as a non-invasive biomarker of fibrosis in children, comparing its performance with that of liver stiffness or other non-invasive scores, as recently highlighted by Kokkorakis and collaborators." (PMID 40650260, 2025). "Multiple potential factors related to the study designs could influence the study results of the GDF15 effects on fibrosis." (PMID 40565178, 2025). "Interestingly, in NAFLD, GDF15 may predict disease severity, advanced fibrosis, and cirrhosis." (PMID 33003626, 2020).
ischemia (20 papers, 2016 to 2025). A hypoperfusion of the BLOOD through an organ or tissue caused by a PATHOLOGIC CONSTRICTION or obstruction of its BLOOD VESSELS, or an absence of BLOOD CIRCULATION. "The protective effects of GDF15 overexpression were approved to be valid in both slight renal injury (55 min of ischemia model) and severe renal injury causing lethal death (60 min of ischemia model)." (PMID 40673270, 2025). "GDF15-deficient mice subjected to ischemia displayed increased leukocyte recruitment in the infarcted zone, leading to higher mortality and a greater infarct size with more apoptotic cardiomyocytes." (PMID 38839839, 2024). "Increased levels of GDF-15 might serve as a marker of pressure overload and subclinical ischemia in healthy individuals since they were associated with 2.7 fold increased risk of cardiovascular events." (PMID 40869494, 2025). "A prolonged increase in GDF-15 levels after episodes of ischemia and reperfusion may be associated with increased levels of oxidative stress, inflammation, and infarct healing, and the increase of GDF-15 requires for enhanced oxidative metabolism and tissue repair." (PMID 27154403, 2016). "It has been consistently shown that GDF15 is synthesized in the cortex and hippocampus of mice and humans, and that it is highly regulated in the brain, for example, by ischemia, aging or Alzheimer’s disease." (PMID 38474863, 2024). "The discriminatory ability of renalase for ischemia prediction was statistically higher compared to those of galectin-3 (DeLong test: p = 0.014) and GDF-15 (DeLong test: p = 0.046) and similar to that of sST2." (PMID 34395559, 2021). "After the occurrence of ischemia‐reperfusion (I/R), the expression of GDF‐15 was sharply enhanced in the cardiomyocytes as an endogenous protective cytokine against I/R‐induced cardiomyocyte apoptosis, possibly through PI3K‐Akt‐dependent signaling pathways." (PMID 30697778, 2019). "GDF15 is overexpressed during intestinal ischemia/reperfusion Injury." (PMID 39687171, 2024). "Additionally, we cannot exclude the possibility that GDF-15 levels spiked during the acute cerebrovascular event as a result of ischemia and inflammation." (PMID 31258506, 2019). "A more recent study by Zhang, reported that the expression of GDF15 was up-regulated in myocardial tissues after undergoing I/R, and that this up-regulation of GDF15 reached a peak at 24h after reperfusion in a rat descending artery ligation myocardia I/R model with 1h ischemia." (PMID 28388574, 2017). "Thus, the observed higher concentration of GDF-15 may be increased secondarily to larger infarction and activation of inflammatory cells involved in microcirculation injury during ischemia followed by reperfusion." (PMID 36615045, 2022). "In patients with LVEF <45% (HFrEF), independent predictors of ischemia were BNP (p = 0.001), renalase (p < 0.001), sST2 (p = 0.004), galectin-3 (p = 0.003), GDF-15 (p = 0.001), and syndecan-1 (p < 0.001)." (PMID 34395559, 2021). "GDF15 is a stress-induced cytokine, produced and secreted by endothelial cells, macrophages, VSMC and cardiac myocytes in response to ischemia, proinflammatory stimuli or oxidative stress." (PMID 33919749, 2021). "Serum samples were obtained and analyzed for GDF-15 (inflammation, remodeling), H-FABP (ischemia and subclinical ischemia), sST2 (inflammation, remodeling) and suPAR (inflammation, remodeling) by means of ELISA." (PMID 32326570, 2020). "These processes comprise subclinical ischemia and ischemic events (H-FABP) as well as cardiovascular remodeling and inflammatory processes (sST2, GDF-15 and suPAR)." (PMID 32326570, 2020). "On the contrary, administering recombinant GDF15 (rGDF15) at reperfusion failed to confer beneficial effects, implying its limited capacity to counteract the detrimental changes that occur during ischemia." (PMID 38839839, 2024).
ischemia (continued). "Our research brings GDF-15 into sharp focus as a potential marker of ischemia/reoxygenation injury and subsequent no-reflow phenomenon." (PMID 36615045, 2022). "In experimental models of ischemia, mRNA and protein levels of GDF15 were increased during the onset and development of no-reflow." (PMID 34445593, 2021). "The AUCs of renalase (0.753), galectin-3 (0.726), and GDF-15 (0.735) were similar and were non-inferior compared to BNP, regarding ischemia prediction." (PMID 34395559, 2021).
bladder cancer (19 papers, 2013 to 2026). "Firstly, fluid-based measurements—notably urinary HMGB1 and urinary VEGF in bladder cancer and serum or tissue assessments of GDF15, HSP90, and S100A9 in renal tumors—provide viable, minimally invasive opportunities to complement imaging and histopathology." (PMID 41009692, 2025). "It is worth noting that they examined several bladder cancer cell lines, including the papilloma bladder cancer cell line, in which GDF-15 is expressed at higher levels compared to the metastatic cell lines." (PMID 39000420, 2024). "In contrast, overexpression of GDF-15 has been shown to decrease cell proliferation and invasion in metastatic bladder cancer cell lines." (PMID 39000420, 2024). "CAPE-induced expressions of NDRG1 and maspin decreased cell proliferation and invasion of bladder carcinoma cells in a GDF15-dependent manner in vitro." (PMID 34662721, 2022). "CAPE stimulated the GDF15 secretion, while being co-treated with rhTGFβ blocked the activation of CAPE on GDF15 secretion from bladder carcinoma, RT-4 and HT1376, cells." (PMID 35884930, 2022). "CAPE also increased the phosphorylation of ERK, JNK and p38 MAPK to modulate the growth differentiation factor 15 (an anti-tumor gene of bladder cancer) expressions in bladder carcinoma cells." (PMID 36421669, 2022). "Our findings indicate that CAPE is a promising agent for anti-tumor growth in human bladder carcinoma cells via the upregulation of GDF15." (PMID 34662721, 2022). "TGFβ/Smad signaling has a role in bladder cancer progression, and GDF15 is an antitumor gene in the human bladder." (PMID 35884930, 2022). "CAPE attenuates proliferation, invasion, and growth of bladder carcinoma cells in vitro and in vivo, inducing the expressions of GDF15, NDRG1, and maspin via ERK, p38, or AMPKα1/2 signaling pathways." (PMID 34662721, 2022). "GDF15, an antitumor gene in bladder carcinoma cells, is abundant in stromal, normal epithelial, and papillary bladder cancer cells." (PMID 34662721, 2022). "Collectively, CAPE treatment induced GDF15 expression and secretion to attenuate the growth of bladder carcinoma HT1376 cells in vivo." (PMID 34662721, 2022). "This study confirmed that CAPE inhibits cell proliferation, invasion, and tumor growth of bladder carcinoma cells via upregulation of GDF15." (PMID 34662721, 2022). "Since then, several reports have confirmed that GDF15 is a methylation-targeted antitumor marker for bladder cancer." (PMID 34662721, 2022). "Whereas, CAPE acts as an antagonist on TGFβ/Smad signaling to block the effect of TGFβ on the GDF15 expression and cell proliferation and invasion in bladder carcinoma cells." (PMID 35884930, 2022). "This is the first report that the HBdSF cells, either fibroblast or smooth muscle cells, as well as human bladder carcinoma cells secret GDF15 in vitro." (PMID 34662721, 2022). "Knockdown of AMPKα1/2 attenuated the CAPE-induced GDF15 expression and cell proliferation in bladder carcinoma cells." (PMID 34662721, 2022). "That is to say, lower expressions of IGF2, GDF15, and KRT13 was associated with lower cell proliferation, invasion, and tumorigenesis of bladder cancer." (PMID 32695477, 2020). "DNA demethylation of GDF15 would upregulate its expression, which led to a suppression of cell proliferation, invasion, and tumorigenesis in bladder carcinoma cells." (PMID 32695477, 2020). "A similar tumor suppressive function was also found for GDF-15, which inhibited the proliferation and invasion of bladder cancer cells in vitro, and attenuated the growth of bladder cancer xenografts in vivo." (PMID 31842336, 2019).
bladder cancer (continued). "The subsequent upregulation of N-cadherin and down-regulation of E-cadherin following GDF15 knockdown in HT1376 cells revealed that GDF15 inhibited the EMT process in bladder carcinoma cells." (PMID 26249737, 2015). "This study determined the expression, regulation, function, and potential downstream target genes of GDF15 in bladder carcinoma cells." (PMID 26249737, 2015). "Our study is the first study to demonstrate the modulations of NDRG1, NDRG2, and NDRG3 gene expressions by GDF15 in bladder carcinoma cells." (PMID 26249737, 2015). "To investigate the role of GDF15 in bladder carcinoma cells, we treated two human bladder cancer cell lines, HT1376 and T24 cells, with recombinant human GDF15 protein (rhGDF15)." (PMID 26249737, 2015). "Human GDF15 expression vector was transfected in bladder carcinoma HT1376 cells to evaluate the function of native GDF15 with regard to cell proliferation and invasion." (PMID 26249737, 2015). "Further in vivo studies in comparison the GDF15 levels in urine with the GDF15 levels in bladder tissues in order to determine GDF15 as the tumor maker of bladder cancer can be warranted." (PMID 26249737, 2015). "Further whole genome profiling assays and the studies of molecular regulatory mechanisms are worthy investigations in determining the downstream genes and the signaling pathways of GDF15 in bladder carcinoma cells." (PMID 26249737, 2015). "The expressions of mammary serine protease inhibitor (MASPIN) and N-myc downstream-regulated family genes (NDRG1, NDRG2, and NDRG3) were upregulated by GDF15 overexpressions and rhGDF15 treatments in bladder carcinoma cells." (PMID 26249737, 2015). "To reconfirm the function of GDF15 in bladder carcinoma cells, we knocked down GDF15 in HT1376 cells." (PMID 26249737, 2015). "GDF15 was also reported as an epigenetic biomarker for detection of bladder cancer from DNA-Based analyses of Urine samples." (PMID 26121976, 2015). "Our findings indicated that GDF15 attenuated cell growth of bladder carcinoma cells in vitro and in vivo." (PMID 26249737, 2015). "The transitional papilloma carcionoma cells (RT4) expressed higher levels of GDF15 as compared with the bladder carcinoma cells (HT1376 and T24)." (PMID 26249737, 2015). "Taken together, our results clearly demonstrated that GDF15 has anti-proliferation and anti-invasion functions in bladder carcinoma cells." (PMID 26249737, 2015). "Notably, GDF15 and HSP90 correlate with ferroptosis susceptibility in RCC and urinary VEGF with HMGB1 increases the chances of non-invasive bladder cancer detection." (PMID 41009692, 2025). "Similar inhibitory effects of GDF15 were observed in colorectal and bladder cancers." (PMID 40144214, 2025). "As a possible mechanism, they suggested that methylation of the GDF-15 gene, which leads to its lower levels in bladder cancer, may contribute to tumor progression." (PMID 39000420, 2024). "CAPE induces GDF15 expressions against the tumor growth of the human bladder carcinoma cells." (PMID 35884930, 2022). "Growth differentiation factor 15 (GDF15) is an antitumor gene of bladder cancer." (PMID 34662721, 2022). "We continued to explore whether the antagonistic effect between GDF15 and TGFβ is dependent on the Smad signaling pathway in bladder carcinoma cells." (PMID 35884930, 2022). "DNA methylation of GDF15 was significantly high in bladder cancer." (PMID 32695477, 2020). "Our results suggest that enhanced expressions of MASPIN and N-myc downstream-regulated family genes and the modulation of EMT may account for the inhibitory functions of GDF15 in the cell proliferation, invasion, and tumorigenesis of bladder carcinoma cells." (PMID 26249737, 2015).
bladder cancer (continued). "The GDF15 should be considered as a tumor suppressor in human bladder carcinoma cells." (PMID 26249737, 2015). "We evaluated the potential downstream target genes of GDF15 in bladder carcinoma cells." (PMID 26249737, 2015). "GDF15 inhibited cell growth in bladder carcinoma cells in vitro and in vivo." (PMID 26249737, 2015). "Upregulations of MASPIN, NDRG1, NDRG2, and NDRG3 expressions may account for the antitumor characteristics of GDF15 in human bladder carcinoma cells." (PMID 26249737, 2015). "In addition to GDF15, factors such as VEGF have been associated with bladder cancer." (PMID 41009692, 2025). "Therefore, we continued to investigate whether TGFβ or CAPE modulated GDF15 and its target genes through the TGFβ/Smad signaling in the human bladder carcinoma cells." (PMID 35884930, 2022). "Costa reported that Vim could associate with GDF15 and TMEFF2 to predict bladder cancer." (PMID 25907256, 2015). "However, further investigation is needed to evaluate whether the levels of GDF15 in the urine or the bladder tissues can be used as the tumor marker for bladder cancer." (PMID 26249737, 2015). "In the present study, our results showed that GDF15 and its downstream genes, maspin and NDRG1 were downregulated by TGFβ through the Smad 2/3 and Smad 1/5 activation in bladder carcinoma cells." (PMID 35884930, 2022). "Previously, GDF15 has been shown to modulate the gene expressions of NDRG1, maspin, and EMT markers to downregulate proliferation, invasion, and tumor growth of bladder carcinoma cells." (PMID 34662721, 2022). "Overall, CAPE upregulates multiple MAPK signaling pathways in bladder carcinoma cells as in OSCC and NPC cells, but the modulation of CAPE in expressions of NDRG1, maspin, and GDF15 occurs via different signals and is cell-dependent." (PMID 34662721, 2022). "Taken together, our results indicated that TGFβ downregulated GDF15 expression via Smad pathways to block its downstream genes, maspin and NDRG1, in bladder carcinoma cells." (PMID 35884930, 2022). "Taken together, CAPE treatment upregulating GDF15 secretion in vitro and in vivo induced the gene expressions of NDRG1 and maspin in bladder carcinoma cells." (PMID 34662721, 2022). "The present study is the first study to indicate that GDF15 and CAPE are the agents that possibly act against the TGFβ/Smad signaling in the human bladder carcinoma cells." (PMID 35884930, 2022). "The objectives of this research are to determine the effect of TGF/Smads on the GDF15 expression and the role of CAPE as a TGF/Smads antagonist in human bladder cancer cells." (PMID 35884930, 2022). "Previously, we reported that GDF15 enhanced the expressions of N-myc downstream-regulated gene 1 (NDRG1) and maspin to downregulate the cell proliferation and invasion in bladder carcinoma cells." (PMID 34662721, 2022). "The rhTGFβ treatment downregulated the GDF15 secretion and being pretreated with SB431542 reversed such an effect in bladder carcinoma HT1376 and RT-4 cells." (PMID 35884930, 2022). "To assess the antagonistic effect of CAPE on TGFβ treatments in bladder carcinoma cells, we treated HT1376 cells with CAPE and/or rhTGFβ to determine the expressions of GDF15, maspin, and NDRG1." (PMID 35884930, 2022). "This study aimed to determine the antitumor effect of CAPE and evaluate the potential molecular mechanisms of CAPE on the expression of GDF15 and its downstream genes, NDRG1 and maspin, in human bladder carcinoma cells." (PMID 34662721, 2022). "Reporter assays using the specific human GDF15 reporter vector revealed that rhTGFβ treatment downregulated the reporter activity of the GDF15 reporter vector; however, being pretreated with SB431542 reversed such an effect in bladder carcinoma HT1376 cells." (PMID 35884930, 2022). "Collectively, our study suggests that GDF15 and CAPE are the potential antagonists for the TGFβ/Smad signaling in the human bladder carcinoma cells." (PMID 35884930, 2022).